GPX4 (glutathione peroxidase 4)
Diseases named in the same sentence as GPX4 in open-access papers (continued):
Sharing a sentence is not in itself a finding about the gene and the disease.
cancer (continued). "In other cancer models, inhibition of complex I attenuated sensitivity to cysteine-deprivation but did not affect GPX4-driven ferroptosis, suggesting a highly cell type specific and context-dependent effect." (PMID 39192032, 2024). "Therefore, we first analyzed the differential expression of GPX4 and SLC7A11 using the TAGG database and found that both were highly expressed in cancer patients." (PMID 39668836, 2024). "These include inhibition of PUFA‐PLs synthesis and peroxidation, restriction of labile iron availability, and upregulation of cellular defense systems such as SLC7A11, GPX4, and FSP1, all of which enable cancer cells to bypass ferroptosis and continue proliferating." (PMID 39568772, 2024). "Interestingly, Kalkavan and colleagues reported that persister cells, which evade apoptosis during targeted cancer therapies involving pro-apoptotic BH3 mimetic compounds, exhibited increased sensitivity to ferroptosis upon GPX4 inhibition." (PMID 38908072, 2024). "Furthermore, the overexpression of GPX4 and FSP1 similarly has an advantage in terms of poor prognosis and cancer progression." (PMID 39723384, 2024). "By inhibiting GPX4, RSL3 disrupts the cellular defense mechanisms against lipid peroxidation, leading to the accumulation of toxic lipid peroxides and subsequent initiation of ferroptosis in cancer cells." (PMID 39544291, 2024). "Furthermore, targeting regulators of ferroptosis, such as AIFM2, glutathione synthetase (GSS), GPX4, FA complementation group D2 (FANCD2), and MAF BZIP transcription factor F (MAFF) can sensitize specific cancers to radiotherapy-dependent ferroptosis." (PMID 38844964, 2024). "However, the adaptive upregulation of SLC7A11 and GPX4 hinders radiotherapy efficacy; hence, inactivating SLC7A11 or GPX4 with ferroptosis inducers yields radioresistant cancer cells and xenograft tumors." (PMID 38844964, 2024). "When SCD1/FADS2 was inhibited in cancer cells, the iron binding capacity decreased and the concentration of the LIP increased, leading to the accumulation of ROS and lipid peroxidation; with GPX4 also being downregulated, this led to ferroptosis." (PMID 39061859, 2024). "Despite its central role in ferroptosis, there is a lack of clear understanding how GPX4 regulates multiple processes in the cell, potentially varying greatly in different cancer types or immune cell populations." (PMID 39188677, 2024). "Additionally, cancer cells often experience increased oxidative stress and are heavily reliant on the antioxidant system, which includes glutathione (GSH) and glutathione peroxidase 4 (GPX4)." (PMID 39766805, 2024). "Taken together, our study reveals a new role of MDH2 in HCC ferroptosis and progression via regulating GPX4, and MDH2, which is highly expressed in HCC, may upregulate GPX4 to mediate ferroptosis evasion, leading to the failure of clinical cancer treatment." (PMID 39519171, 2024). "One of the reasons for the results in this study, which are contrary to the clinicopathological hypothesis based on the functions of GPX4 and FSP1, may be the effect of oxidative stress, including lipid peroxidation, on the genome of cancer cells." (PMID 39594843, 2024). "We systematically interrogated the Cancer Therapeutics Response Portal datasets, and found that E2F4 expression correlated with resistance to ferroptosis inducers ((RSL3, ML210 and ML162, which inhibit GPX4 activity)." (PMID 38575587, 2024). "Several studies have revealed that inhibition of GPX4 does not initiate ferroptosis in some cancer cell lines, suggesting the existence of alternative antiferroptosis regulators in cancer cells." (PMID 39309443, 2024). "In addition, bioinformatics analyses showed that SLC7A11 and GPX4 expression (two critical regulators of ferroptosis) are increased in LUAD and LUSC patients and their expression were correlated with the individual cancer stages of LUAD and LUSC." (PMID 38561419, 2024).
cancer (continued). "Collectively, the interplay between GSH, GPX4, and cellular resilience highlights the potential of GSH-targeted strategies to improve the efficacy of standard treatments and possibly alleviate drug resistance in cancer therapy." (PMID 39090114, 2024). "In cancer cells, the labile iron pool and increase in lipid content and ACSL4 expression may lead to a GPX4-dependent increase, resulting in vulnerability to GPX4 inhibitors." (PMID 39174525, 2024). "Therefore, targeting GCH1, in addition to depleting GPX4 and FSP1, can effectively induce ferroptosis in cancer cells that are resistant to apoptosis." (PMID 39723384, 2024). "Notably, overexpression of LASS2 reversed the changes in these cancer cells, such as changes in metastasis and ferroptosis-related protein levels (EMT, TFRC, GPX4, FTH1 and FTL1), induced by Fer-1 or erastin." (PMID 38419028, 2024). "IR can induce SLC7A11 and GPX4 upregulated as an adaptive response to safeguard cells against ferroptosis and contribute to radioresistance, suggesting that inhibiting SLC7A11 or GPX4 sensitizes radioresistant cancers to IR." (PMID 38453898, 2024). "While these compounds principally target GPX4, they might also exert effects on TXNRD1 in A549 and H1975 cancer cells." (PMID 39090114, 2024). "GPX4 is the major enzyme using GSH as the cofactor in catalyzing the reduction of PLOOHs in mammalian cells, hence serving as a central inhibitor of ferroptosis in cancer cells." (PMID 38443363, 2024). "Several mechanisms involved in ferroptosis, including system Xc-, GPX4, lipid peroxidation, and GSH metabolism, mediate biological processes such as oxidative stress and iron overload and appear to be dysregulated in many cancer types." (PMID 38539832, 2024). "In summary, CeO2-based nanozymes could be clinically translated as novel antioxidants and synergetic GPX4 activators to inhibit cardiomyocyte ferroptosis, thereby mitigating DIC in cancer patients, while improving their prognosis and quality of life." (PMID 36904089, 2023). "When the enzymatic activity of GPX4 is inhibited and (CAP-generated) RONS interact with the cell membrane, it increases the level of Fe2+ and lipid peroxidation, ultimately inducing ferroptotic cancer cell death." (PMID 37759771, 2023). "For instance, following radiotherapy, cancer cells may undergo an adaptive response by increasing SLC7A11 and GPX4 levels." (PMID 37240889, 2023). "While it is out of the scope of this review to outline all the complex interconnections between ferroptosis, cancer and drug resistance, we want to point out three promising drug targets at this interface, namely NRF2, SLC7A11, and GPX4, and refer to comprehensive review articles in this field." (PMID 36658724, 2023). "Hence, only combined targeting of GPX4 and FSP1 is effective at killing KRAS-driven pancreatic organoids and FSP1 is upregulated in human KRAS-driven cancers." (PMID 36443441, 2023). "TGF-β can promote EMT of cancer cells by inducing ZEB1 and enhancing GPX4 inhibitor activity." (PMID 38023171, 2023). "While the significance of selenium to GPX4 in cancer therapy has not yet been explored, common approaches to GPX4-relevant cancer therapy involve downregulating GPX4-induced antioxidation, a well-known method of activating ferroptosis." (PMID 36675129, 2023). "In contrast, a worse prognosis was observed in cases with higher or less GPX4 expression in cancer tissues than in noncancerous tissues." (PMID 37626774, 2023). "Together, these in vivo results demonstrated that GPX4 could promote the host antitumor immune response of COAD and enhance the efficacy of cancer immunotherapy." (PMID 38065948, 2023).
cancer (continued). "In cancer cells, low concentrations of compound 55 (12.5–100 nM) augmented intracellular ROS and MDA levels, depleted intracellular GSH, and decreased the expression of GPX4, SLC7A11, and SLC40A1." (PMID 36658724, 2023). "GPX4 has been shown to be critical for survival of lapatinib‐resistant cancer cells, but not lapatinib‐naïve cancer cells." (PMID 35906899, 2023). "The iron could trigger Fenton reaction to generate LPO, while BSO could inactivate GPX4 to lower the rate of LPO reduction, which finally achieved collaborative inhibition of cancer by inducing efficient ferroptosis." (PMID 37563614, 2023). "Various experimental cancer models have shown that ferroptosis inducers, that target ferroptosis-suppressor-protein 1 (FSP1) and glutathione peroxidase 4 (GPX4), deplete glutathione (GSH), or enhance the iron pool, can effectively kill cancer cells, especially drug-resistant cancer cells." (PMID 36816957, 2023). "Due to the role played by GSH in regulating redox balance, some molecules involved in GSH metabolism, such as glutathione peroxidase 4 (GPX4), GCLC and the cystine transporter solute carrier family 7 member 11 (SLC7A11), have been reported to inhibit the ferroptosis of cancer cells." (PMID 37443154, 2023). "Zn-induced cancer cells mirrored the mechanistic hallmarks of Fe-induced cells, including elevated ROS (despite zinc being a redox-inactive metal), lipid oxidation, depleted GSH and downregulated GPX4." (PMID 36835045, 2023). "We assume that the induction of ferroptosis by inhibiting GPX4 and GSH might have superb potential for cancer therapy." (PMID 36482419, 2022). "For example, nanoplatform could inhibit the expression of HMGCR to downregulate the mevalonate (MVA) pathway and glutathione peroxidase 4 (GPX4), thereby producing more LPO to induce cancer cell ferroptosis." (PMID 35941905, 2022). "Current drugs used to treat cancer through ferroptosis include erastin, sorafenib and sulfasalazine which inhibit the Xc-system by inhibiting cysteine transport thereby blocking GSH synthesis and GPx4 function." (PMID 36591540, 2022). "In xenograft models of athymic nude mice subcutaneously injected with shNT-GPX4-iKO cells and shNF2-GPX4-iKO cells, knockdown of NF2 upregulates TFRC, ACSL4 and nuclear YAP, and doxycycline-induced GPX4 knockdown is able to eliminate cancer lesions." (PMID 35847022, 2022). "Studies reveal that the proliferation of cancer cells was not obviously effected only by down-regulating the expression of GPX4." (PMID 36551145, 2022). "Intracellular cystine can be rapidly reduced to cysteine for the synthesis of glutathione (GSH), which thereby serves as a co‐factor for glutathione peroxidase (GPX4) to reduce lipid peroxide, constraining PLOOH levels that would otherwise trigger ferroptotic death of cancer cells." (PMID 35604883, 2022). "A recent study demonstrated that depletion of arginine repressed Erastin-induced, but not GPX4-induced, ferroptosis across a spectrum of cancer cell lines." (PMID 35065965, 2022). "Therefore, GPX4 inhibitors (e.g., RSL3) should be delivered specifically to the cancer cells to prevent side effects." (PMID 35422492, 2022). "However, a large variety of cancer cells have insufficient or downregulated expression of ACSL4, so that they are resistant to GPX4-mediated ferroptosis." (PMID 36517470, 2022). "As HIF2α is absent, cancer cells develop tolerance to GPX4 inhibitors and reduce the occurrence of ferroptosis." (PMID 35911967, 2022). "In cancer cells, interactions between MTOR and GPX4 can regulate autophagy-dependent ferroptosis by inhibiting CMA, and MTOR inhibitors may promote GPX4 degradation by activating the CMA pathway." (PMID 36093072, 2022).
cancer (continued). "Interestingly, pharmacological inhibitors of FSP1 such as iFSP1 synergizes with GPX4 modulation to trigger ferroptosis in FSP1 overexpressed cells, and iFSP1 can sensitize several cancer cells to ferroptosis." (PMID 35805884, 2022). "During cancer therapeutic process, we found that zinc ions released from Zn-Fu MNs was able to damage mitochondria, the main site of ROS production, to generate severe inflammatory reaction 47 which induced GSH depletion and GPX4 down-expression." (PMID 36168615, 2022). "GPX4, another main antioxidant defense, can directly reduce cell membrane phospholipid hydroperoxide to hydroxyphospholipid, taking advantage of GSH as a substrate, resulting in the suppression of ferroptosis in cancer cells." (PMID 35342359, 2022). "In addition to proferroptotic cancer treatment, bioactive ferroptosis inhibitors, which are usually antioxidants that restore GSH/GPX4 levels, have also been clinically investigated to treat other diseases." (PMID 35118067, 2021). "We next examined the sensitivity of these cancer and noncancer cells to prolonged exposure to agents targeting the xCT and GPX4 anti-ferroptotic machinery, Erastin and Rsl-3." (PMID 33672555, 2021). "Although GPX4 is essential for cancer cells to escape from ferroptosis, inhibition of GPX4 fails to trigger ferroptosis in some cancer cells regardless of ACSL4 expression, suggesting the existence of additional mechanisms of ferroptosis resistance." (PMID 33868986, 2021). "We also analyzed the mRNA levels of SLC7A11, GPX4, and AIFM2 in pan-cancer using Oncomime database." (PMID 34722530, 2021). "Erastin, GPX4 inhibitors and some drugs (e.g., sorafenib, sulfasalazine, artesunate, cisplatin, ibuprofen, lanpersone and DHAN) trigger ferroptosis in various types of cancers, but other types of cell death contribute to their anticancer activity as well." (PMID 33268902, 2021). "The ubiquitously expression of GPX1,GPX4,TXNRD1 and TXNRD2 in humans has been reported in previous studies, and our study further confirmed these genes were also ubiquitously expressed in different types of cancer." (PMID 33706760, 2021). "On the other end, the pro-drug GPX4 inhibitor ML210 and its derivative, JKE-1674, have shown higher specificity and favorable bioavailability that maybe exploited for cancer therapy." (PMID 34485382, 2021). "αESA does not alter GPX4 activity but is incorporated into cellular lipids and promotes lipid peroxidation and cell death in diverse cancer cell types." (PMID 33854057, 2021). "Thus, the development of effective GPX4 covalent inhibitors, such as ML210, has gradually aroused general interest in anti-cancer drug research." (PMID 35118077, 2021). "Further experiments showed that SIM could inhibit the expression of HMGCR to downregulate the mevalonate (MVA) pathway and glutathione peroxidase 4 (GPX4), thereby inducing cancer cell ferroptosis." (PMID 34627266, 2021). "Prognostic values of SLC7A11, GPX4, and AIFM2 in pan-cancer in Kaplan–Meier database." (PMID 34722530, 2021). "Besides, we discovered that cancer cells with silencing of circGFRA1 displayed a reduction in the glutathione (GSH)/oxidized glutathione (GSSG) ratio and knockout of glutathione peroxidase 4 (GPX4)." (PMID 34668628, 2021). "The tractability of these dietary, pro-ferroptotic fatty acids addresses the current lack of effective GPX4 inhibitors for use in vivo and suggests an opportunity to exploit a metabolic liability across cancer subtypes." (PMID 33854057, 2021). "Compared with erastin, RSL3 has been found to reprograms cancer cell metabolism by regulating GPX4 without modulating system XC−, but its downstream signaling pathways are similar to those of erastin." (PMID 33665167, 2020). "Cancer cells challenged with palladium pyrithione complex (PdPT), a pan-deubiquitinase (pan-DUB) inhibitor, undergo apoptosis and ferroptosis with caspase activation and GPX4 protein degradation." (PMID 33294126, 2020).
cancer (continued). "In parallel to the canonical GPX4 pathway, the ferroptosis suppressor protein (FSP1) positively correlates with ferroptosis resistance across hundreds of cancer cell lines and FSP1 mediates resistance to ferroptosis in lung cancer cells in culture and mouse tumor xenografts." (PMID 32516941, 2020). "Furthermore, BRD4 expression was positively related to GPX4, SLC7A11, and SLC3A2 expression in pan-cancer patients." (PMID 30988278, 2019). "Since the activity of GPx4 relies on GSH, we therefore tested whether GPx4 inhibitors and other ferroptosis inducers can enhance each other in killing cancer cells." (PMID 31527591, 2019). "FSP1 functions in parallel to GPX4 to mitigate lipid peroxidation through its NAD(P)H-dependent oxidoreductase activity, which reduces CoQ10 to ubiquinone (CoQH2) or vitamin K to VKH2, rendering tumors resistant to ferroptosis and representing a promising target to trigger cancer cell death." (PMID 39881208, 2025). "This GAG–lipoprotein axis represents a previously unrecognized extracellular mechanism for acquiring ferroptosis protection, distinct from intracellular systems such as GPX4 or FSP1, and may provide therapeutic opportunities for targeting ferroptosis-resistant cancers." (PMID 41008983, 2025). "However, no GPX4 inhibitors have reached clinical studies for cancer therapy in humans, since all conventional GPX4 inhibitors including RSL3 have had limited prospects for further clinical development due to their poor selectivity and pharmacokinetics." (PMID 39369284, 2025). "In other cancer types, GPX4 genetic alterations did not significant effect OS or DFS." (PMID 41142608, 2025). "Consequently, ferroptosis‐related genes that suppress GPx4 expression and enzymatic activity, elevate intracellular iron levels, and enhance PUFA peroxidation have been widely explored as potential therapeutic targets in cancer treatment." (PMID 40159622, 2025). "Moreover, no significant alterations in GPX4 methylation levels were observed in other types of cancer." (PMID 41142608, 2025). "However, cancer cells counteract this by enhancing antioxidant defenses, notably through GPX4, SLC7A11, and FSP1, which mitigate ferroptosis and sustain cell survival." (PMID 39935430, 2025). "The ablation of key autophagy or lysosome-dependent cell death effectors, such as STAT3 and cathepsin B, could inhibit ferroptotic cancer cell death, whereas the knockout of SLC7A11 or GPX4 could reduce autophagy, thereby providing further protection against ferroptosis induced by Golgi stress." (PMID 41462678, 2025). "In general, cancer cells with stemness-like characteristics can enhance the antioxidant defense system by up-regulating NRF2 transcription factor expression, promoting the metabolism level of glutathione (GSH), or increasing the activity of glutathione peroxidase 4 (GPX4)." (PMID 40236810, 2025). "Finally, the study does not explore other potential non-canonical functions of ADAR1 beyond the miR-335-5p/Sp1/GPX4 pathway, leaving gaps in understanding its broader role in cancer biology." (PMID 40852728, 2025). "However, in GPX4 high expression cancer cells, the MCI inhibitor did not induce ferroptosis, but increased cell sensitivity to ferroptosis induced by the GPX4 inhibitor." (PMID 40185704, 2025). "One study identified N6F11 as a selective ferroptosis inducer that degrades GPX4 specifically in cancer cells without affecting immune cells, thereby triggering ferroptosis in cancer cells and initiating HMGB1-dependent antitumor immunity mediated by CD8+ T cells." (PMID 40733146, 2025). "Interestingly, tubastatin A, a selective HDAC6 inhibitor, overcomes both ferroptosis resistance and radioresistance in cancer cells by inhibiting GPX4 enzymatic activity, independent of histone deacetylase 6 (HDAC6) inhibition." (PMID 39534872, 2024).